RNU6-776P (RNA, U6 small nuclear 776, pseudogene)
Gene: Small nuclear RNA gene on chromosome 1 (22,010,985 to 22,011,088, forward strand). Ensembl gene ENSG00000201273.
Homologues: Orthologues: mouse Gm25039 (89% identical), macaque U6 (83% identical), guinea pig U6 (66% identical). Paralogues in human: RNU6-1022P (95% identical), RNU6-797P (91% identical), RNU6-1309P (87% identical), RNU6-454P (87% identical), RNU6-697P (87% identical), RNU6-742P (87% identical), RNU6-1083P (86% identical), RNU6-1091P (86% identical), RNU6-1123P (86% identical), RNU6-1145P (86% identical), RNU6-1159P (86% identical), RNU6-11P (86% identical), and 1287 more.